CXCL9 (C-X-C motif chemokine ligand 9)
Diseases named in the same sentence as CXCL9 in open-access papers (continued):
Sharing a sentence is not in itself a finding about the gene and the disease.
dysplasia (1 paper, 2021). A usually neoplastic transformation of the cell, associated with altered architectural tissue patterns. "The transcript levels of Th1-associated chemokines/cytokines (Cxcl9, Cxcl10, Ccl5, and Ifng) and the Th1-associated chemokine receptor Cxcr3 were upregulated in dysplasia, whereas the expression of these Th1-associated genes was decreased in SCC." (PMID 33921389, 2021).
esophagitis (1 paper, 2026). An acute or chronic inflammatory disease affecting the esophageal wall. "In contrast, EoE-like esophagitis was primarily immune-driven, marked by CXCR3 ligand activation (CXCL9, CXCL10, CXCL11) and immunoglobulin complex enrichment, indicating systemic immune dysregulation and a potential precursor state to conventional EoE." (PMID 41818315, 2026).
experimental autoimmune encephalomyelitis (1 paper, 2022). An autoimmune demyelinating disease of the central nervous system that is produced experimentally in animals by the injection of homogenized brain or spinal cord in Freund's adjuvant. "Moreover, the upregulation of Ccl2, Ccl3, Ccl4, Ccl7, Cxcl9, and Cxcl10 is also related to the acute phase of experimental autoimmune encephalomyelitis." (PMID 35911717, 2022).
fibromyalgia (1 paper, 2025). A chronic disorder of unknown etiology characterized by pain, stiffness, and tenderness in the muscles of neck, shoulders, back, hips, arms, and legs. "CXCL9 may be elevated in patients who have chronic pain conditions, such as fibromyalgia." (PMID 40649738, 2025).
fracture (1 paper, 2022). "In a fully adjusted model, every 10% increment in serum CXCL9 levels was associated with a significant OR (95% CI) of 1.17 (1.06, 1.29) for the risk of hip fracture in men." (PMID 35810382, 2022).
fungal keratitis (1 paper, 2023). "We identified 60 viral genes and 327 bacterial/fungal genes with an AUC of at least 0.9, among them MATR3, CXCL9, and KCNA3 for viral keratitis, and S100A8, CXCL8, and CCL20 for bacterial/fungal keratitis." (PMID 38274739, 2023). "MATR3 (AUC = 0.95), CXCL9 (AUC = 0.95), and KCNA3 (AUC = 0.90) were among the best candidate markers for viral keratitis, and S100A8 (AUC = 1), CXCL8 (AUC = 1), and CCL20 (AUC = 1) were among the best candidates for bacterial/fungal keratitis." (PMID 38274739, 2023).
gallbladder cancer (1 paper, 2026). "In addition, our cohort study showed that high CXCL9 and low LGALS4 in the liver invasion margin demonstrated a favorable prognosis and better responses to anti-PD-1 immunotherapy for patients with gallbladder cancer." (PMID 41766656, 2026).
gastric tumor (1 paper, 2020). "In this study, we investigated the gastric tumor response to radiation therapy, based on the Sting signal, IFNB1, TNFα, CXCL-9 as well as IL-10 gene expression, infiltration of DCs, Th and Teff cells in the tumor microenvironment, and PD-1/PD-L1 expression after radiation therapy." (PMID 32960261, 2020).
Gaucher disease (1 paper, 2021). Gaucher disease (GD) is a lysosomal storage disorder encompassing three main forms (types 1, 2 and 3), a fetal form and a variant with cardiac involvement (Gaucher disease - ophthalmoplegia - cardiovascular calcification or Gaucher-like disease). "Here, we delineate role of the CXCR3 receptor and its exogenous C-X-C motif chemokine ligand 9 (CXCL9) in induction of increased tissue recruitment of CD4+ T and CD8+ T cells in Gaucher disease." (PMID 34884512, 2021).
genital herpes (1 paper, 2025). Herpes simplex infection of the genitals, most commonly caused by the herpes simplex-2 virus. "Instead, the spontaneous production of IFN-α, IFN-β, IFN-ω, IL-29, CXCL9, and perforin could imply that HSV-2 meningitis generates a more pronounced systemic innate immune response leading to stronger trained innate immunity, and epigenetic imprinting than HSV-2 genital herpes." (PMID 40534882, 2025).
germinoma (1 paper, 2010). A malignant germ cell tumor arising in the central nervous system. "Six genes (BANK1, CXCL9, CXCL11, DDIT4L, ELOVL6 and HERC5) within 4q13.3-4q28.3 were more abundant in germinomas." (PMID 20178649, 2010).
glomerulonephritis (1 paper, 2025). A renal disorder characterized by damage in the glomeruli. "The CXCL9/CXCL10-CXCR3 axis is a target of the CS-mediated depletion of CD4pos T cells in glomerulonephritis." (PMID 41229420, 2025).
hantavirus infections (1 paper, 2023). "Analyzing the immune response, elevated concentrations of specific chemokines (CCL2 and CXCL9) were detected, suggesting their role in the immunopathogenesis of severe hantavirus infections." (PMID 38138107, 2023).
heart transplant (1 paper, 2010). "We found that PECAM1, CXCL9 and CD44 proteins were significantly upregulated in the serum/plasma samples of both renal and heart transplant patients with acute rejection compared with patients with stable graft function." (PMID 20885780, 2010).
hemorrhagic fever (1 paper, 2017). An infectious disease caused by certain viruses or bacteria that can damage the walls of tiny blood vessels, making them leak, and can hamper the blood's ability to clot and cause severe, life-threatening illness. "Hemorrhagic fever with renal syndrome cases were characterized by a strong expression of MIF, IL-12p40, IL-3, IL-16, CXCL9, CCL27, CXCL1, and HGF." (PMID 28572804, 2017).
hip fracture (1 paper, 2022). Traumatic or pathological injury to the hip in which the continuity of either the femoral head, femoral neck, intertrochanteric or subtrochanteric regions is broken. "Correspondingly, we also showed that CXCL9 had a positive association with the risk of hip fracture only in men." (PMID 35810382, 2022).
hyperthyroidism (1 paper, 2021). Overactivity of the thyroid gland resulting in overproduction of thyroid hormone and increased metabolic rate. "A prevalent Th1-immune response (not related to the hyperthyroidism per se, but to the autoimmune process) is reported in the immune-pathogenesis of GD and GO; Th1-chemokines (CXCL9, CXCL10, CXCL11) and the (C-X-C)R3 receptor are crucial in this process." (PMID 33935970, 2021).
hypoglycaemia (1 paper, 2024). "In addition, CXCL9, CCL23, CCL3 and CLL4 increased in response to hypoglycaemia, which can recruit immune cells, thus potentially contributing to the persistently elevated levels of circulating white blood cells." (PMID 38331900, 2024).
immunodeficient diseases (1 paper, 2022). "The functional capacities of the highly expressed DEGs in the Chinese Simmental cattle mainly focused on inflammatory diseases (CXCL9 and FCRL1), immunodeficient diseases (ADM2, CCL5, and CAMKV), carcinoma (CXCL11, JAKMIP2, GZM, and DNAAF1), and GTP binding and GTPase activity (NUGGC)." (PMID 35495650, 2022).
infectious encephalitis (1 paper, 2022). An acute infectious process that affects the brain tissue. "The subgroup analysis for the infectious encephalitis revealed significantly increased levels of CXCL9 in the CSF (SMD, 3.58; 95% CI, 3.02–4.14; P < 0.01)." (PMID 36048783, 2022). "Contrastingly, CXCL9 had a higher concentration in infectious encephalitis." (PMID 36048783, 2022).
intrahepatic cholangiocarcinoma (1 paper, 2021). A carcinoma that arises from the intrahepatic bile duct epithelium in any site of the intrahepatic biliary tree. "Endogenous CXCL9 affects tumor progression and postoperative survival in intrahepatic cholangiocarcinoma patients by regulating tumor-infiltrating NK cells, which was also validated in mouse models." (PMID 33854600, 2021).
invasive breast carcinoma (1 paper, 2013). A carcinoma that infiltrates the breast parenchyma. "Indeed, we saw a dramaticincrease in tumor cell expression of the T cell chemokine CXCL9 in COX-2MECKOtumors, consistent with a recent report in patients with invasive breast cancer thattumor cells are the major source of CXCL9." (PMID 24004819, 2013).
invasive carcinoma (1 paper, 2021). A carcinoma that is not confined to the epithelium, and has spread to the surrounding stroma. "However, S100A8, LAG3, CXCL10, CXCL9 and BIRC5 showed a difference in fold change between DCIS and invasive carcinoma although statistically not significant (adjusted p value > 0.05)." (PMID 34504204, 2021).
lacrimal gland disease (1 paper, 2018). "Since C57BL/6.NOD-Aec1Aec2 mice are distinct from NOD and MRL/lpr mice, it is possible that the contributions of CXCL9 to lacrimal gland disease is different in this particular mouse strain." (PMID 30347820, 2018).
leptospirosis (1 paper, 2024). A contagious bacterial infection caused by spirochetes of the genus Leptospira. "Regarding CXCL9, we showed that mice susceptible to leptospirosis (HeJ) had lower levels of this chemokine when compared to resistant mice (Balb/c), suggesting that it plays an important role in the host response." (PMID 39534703, 2024). "The main findings were that CCL5, CXCL5, and CXCL9 are highly expressed during leptospirosis, indicating a special role of these molecules in the immunity and pathogenesis of the disease." (PMID 39534703, 2024). "The main findings in our study were that CCL5, CXCL5, and CXCL9 are highly expressed in human leptospirosis disease." (PMID 39534703, 2024). "The correlation analysis of detected chemokines CXCL11, CXCL9, CCL3, and CCL2 helps to clarify the role of each cytokine in leptospirosis." (PMID 39534703, 2024). "Moreover, CCL5 and CXCL9 together have been correlated with CD8+ T-cell infiltration, indicating an important role in the control of leptospirosis." (PMID 39534703, 2024).
liver dysfunction (1 paper, 2025). "Among these chemokines, CXCL9 and CXCL10 showed the strongest association with advanced severity of liver dysfunction as defined by CTP, MELD-Na, and MELD 3.0 scores and were predictive of 30-day mortality." (PMID 41373861, 2025). "In particular, CXCL9 and CXCL10 may have potential for discrimination of severe liver dysfunction and poor short-term prognosis." (PMID 41373861, 2025).
lupus erythematosus (1 paper, 2025). An autoimmune, connective tissue chronic inflammatory disorder affecting the skin, joints, kidneys, lungs, heart, and the peripheral blood cells. "In lupus erythematosus, IFNs, particularly IFN-κ and IFN-α, amplify inflammatory cascades in the skin characterized by cytokines such as IL-6, IL-1β, and TNF-α, and chemokines (CXCL9, CXCL10), resulting in sustained immune cell infiltration." (PMID 41479908, 2025).
mental disorder (1 paper, 2025). A disease that has its basis in the disruption of mental process. "Elevated levels of CXCL9 in mental disorders may arise from mechanisms involving interferon-γ-induced neuroinflammation, systemic inflammation, and inflammaging, which disrupt the integrity of the blood-brain barrier." (PMID 40650062, 2025).
Miscarriage (1 paper, 2025). A pregnancy that ends at a stage in which the fetus is incapable of surviving on its own, defined as the spontaneous loss of a fetus before the 22th week of pregnancy. "In addition, CXCL9 protein expression correlated with miscarriage history." (PMID 41280905, 2025).
monocytic leukemia (1 paper, 2021). "We further evaluate the role of CXCL9 in the migration and activation of macrophages using mouse peritoneal macrophages and a human monocytic leukemia cell line (THP-1)." (PMID 33510341, 2021).
mood disorder (1 paper, 2024). A cognitive disorder a disturbance in which the person's mood is hypothesized to be the main underlying feature. "The limitation of using a complex, partially characterized stimulant like LPSCM is that factors which may not be relevant to mood disorders, such as LPS, higher levels of chemokines like CXCL9 and CXCL10, could have also influenced the glial cells significantly." (PMID 39539342, 2024).
mucosa-associated lymphoid tissue lymphomas (1 paper, 2024). "This response may be accompanied by IL-8, IL-2, CXCL-9 and CXCL-10 to the site of inflammation, with excess immune overstimulation by persistent antigens creating B-lymphocyte hyperplasia, triggered by T-cells, which can lead to mucosa-associated lymphoid tissue lymphomas." (PMID 39608222, 2024).
multinodular goiter (1 paper, 2021). Nodular goiter characterized by more than one discrete tissue mass. "Another study found that circulating CXCL9 and CXCL11 levels were significantly elevated in patients with AIT compared with euthyroid controls or patients with multinodular goiter." (PMID 34868029, 2021). "A study showed that circulating CXCL9 and CXCL10 levels were significantly elevated in patients with AIT compared with normal controls or patients with multinodular goiter." (PMID 34868029, 2021).
myelofibrosis (1 paper, 2023). A partial or complete replacement of the bone marrow stroma by fibrous tissue. "It was characterized by interleukin (IL)-6, IL-18, IL-18 binding protein (BPa), and CXCL9 chemokine hypercytokinemia accompanied by myelofibrosis." (PMID 37347054, 2023).
neurosyphilis (1 paper, 2023). Infection of the brain or spinal cord by Treponema pallidum. "Meanwhile, the increased levels of CXCL9, CXCL7, CCL24, IL-17, IL-26, and migration inhibitory factor (MIF) of macrophages in the CSF of neurosyphilis patients suggested their role as promising differential diagnostic tools for neurosyphilis." (PMID 38105236, 2023).
ocular infection (1 paper, 2020). "However, the UL13 kinase-dead repaired mutant virus produced less mortality in infected CXCL9-deficient mice than in wild-type mice, suggesting that CXCL9 expression is also required for the mortality of mice following ocular infection." (PMID 33256093, 2020). "In addition, HSV-1 UL13 was shown to mediate downregulation of CXCL9 expression in the brains of mice following ocular infection." (PMID 33256093, 2020).
ocular sarcoidosis (1 paper, 2016). A leading cause of inflammatory eye disease is sarcoidosis. "Serum levels of CXCL9 and CXCL10 have been correlated with serum ACE levels in presumed ocular sarcoidosis." (PMID 26879979, 2016).
ocular toxoplasmosis (1 paper, 2023). Ocular toxoplasmosis is an infection in the eye caused by the parasite, Toxoplasm a gondii. "In another study, patients with ocular toxoplasmosis displayed high levels of IFN-induced chemokines CXCL9 and CXCL10 and circulating chemokines CCL25, CCL11, CXCL12, CXCL13, and CCL2." (PMID 36755348, 2023).
oral lichen planus (1 paper, 2017). Oral lichen planus is a chronic inflammatory oral condition of unknown aetiology characterized by T-cell-mediated chronic immune response and abnormal epithelial keratinization cycle. "CXCL9/10/11 were also assessed in tissues from normal patients and those with oral lichen planus (OLP)." (PMID 28253295, 2017).
oropharynx carcinoma (1 paper, 2023). A primary or metastatic malignant neoplasm that affects the oropharynx. "In this manuscript, we demonstrated a particular chemokine axis (CXCR3/CXCL9,10,11) to be highly expressed in HPV-associated oropharynx carcinoma (HPVOPC)." (PMID 37686653, 2023).
Pan (1 paper, 2021). "Pan cancer analysis and the tumor immune microenvironment analysis further suggested that CXCL9 has greater importance in cancer immunotherapy than other prognostic biomarkers." (PMID 35052427, 2021).
paraganglioma (1 paper, 2023). A benign or malignant neoplasm arising from paraganglia located along the sympathetic or parasympathetic nerves. "It was found that XCR1 and CXCL9 have a significant positive correlation in a variety of tumors, including THCA, SKCM, SARC, KIRC, TGCT, BRCA, PCPG (pheochromocytoma and paraganglioma), and KIRP." (PMID 37895310, 2023).
PFAPA syndrome (1 paper, 2010). An auto inflammatory syndrome characterized by recurrent febrile episodes associated with aphthous stomatitis, pharyngitis and cervical adenitis. "Elevated levels of the IFNγ-induced chemokines CXCL9/MIG and CXCL10/IP10 in the absence of Th2- and Th17-associated cytokines indicated that components of a Th1-type inflammatory response coincide with fever in PFAPA syndrome." (PMID 20819226, 2010).
pneumococcal infection (1 paper, 2020). Infections with bacteria of the species streptococcus pneumoniae. "As expected, CXCL9, − 10, and − 11 secretions were significantly decreased with prior PM2.5 exposure, followed by bacterial challenge, compared with that with pneumococcal infection alone." (PMID 32753046, 2020). "Our results expanded the prior findings and showed that CXCL9, − 10, and − 11 expression in BALF was significantly increased after pneumococcal infection, but decreased upon PM2.5 treatment." (PMID 32753046, 2020). "Decreases in CXCL9, − 10, and − 11 levels reduced CXCR3 and PI3K/Akt expression in PM2.5 + pneumococcus co-treated macrophages, compared with that for pneumococcal infection alone." (PMID 32753046, 2020).
polymyositis (1 paper, 2014). A rare idiopathic inflammatory myopathy characterized by symmetric proximal muscle weakness and elevated muscle enzymes. "In previous reports on IIMs, CXCL10 was abundantly expressed on macrophages and T cells in polymyositis, inclusion body myositis and dermatomyositis whereas CXCL9 and CXCL11 were not altered compared to the control." (PMID 24939012, 2014). "However, we chose CXCL10 in this study because its expression is abundant in the muscle tissue of CIM in this study and polymyositis unlike CXCL9 or CXCL11." (PMID 24939012, 2014).
primary immunodeficiency (1 paper, 2020). "As primary immunodeficiency-related genes were correlated with TfR1 low-expressed cells, we detected fold changes of PD-L1, CXCL9, and CXCL10 mRNA levels in TfR1-knockout cells, which were enhanced after IFN-γ treatment." (PMID 32024821, 2020).
psittacosis (1 paper, 2022). "We found significant upregulated expression of multiple chemokines and receptors (CXCL1, CXCL9, and CXCL10/IP-10) in severe psittacosis cases." (PMID 36119044, 2022).
pterygium (1 paper, 2022). A wedge-shaped fibrovascular lesion arising from the bulbar conjunctiva and extending to the cornea. "In active pterygium, genes involved with immune and inflammatory response (CXCL9 and PLA2G2D), angiogenesis (SERPINB5 and BM4), keratinization (DSG1), response to UV light (TYR) and negative regulation of apoptotic process (PIM1) are up regulated in relation to atrophic pterygium." (PMID 34997134, 2022).
pulmonary edema (1 paper, 2019). Accumulation of fluid in the lung tissues causing disturbance of the gas exchange that may lead to respiratory failure. "CXCL-9, another cytokine that was increased in patients with pulmonary edema, was also one of the most upregulated genes in EV71- and CVA16-infected gerbils." (PMID 31906004, 2019).
pulmonary sarcoidosis (1 paper, 2023). Sarcoidosis affecting the lung parenchyma. "CXCR3 ligands, CXCL9 and CXCL11, are augmented in BALF from pulmonary sarcoidosis." (PMID 36949950, 2023).
rash (1 paper, 2017). "These analyses showed that serum CXCL9 and CXCL10 levels were elevated in AOSD patients with an evanescent rash compared with patients who did not display such a manifestation." (PMID 28436448, 2017). "An analysis of serum chemokine levels with regard to AOSD manifestations showed that patients with a skin rash had a higher level of CXCL9 (667.6 ± 823.2 vs. 105.8 ± 84.8 pg/mL, p = 0.024) and CXCL10 (251.6 ± 191.2 vs. 79.4 ± 45.6 pg/mL, p = 0.021) than those without a rash." (PMID 28436448, 2017).
retinal diseases (1 paper, 2018). "The finding that elevated levels of MIG/CXCL9 were apparent only in treated wet AMD could suggests that this change is not only age-related, but also a marker of retinal diseases with inflammatory components such as AMD at a late, steady-state stage, which deserves further attention." (PMID 30157273, 2018).